FANCD2 (FA complementation group D2)
Diseases named in the same sentence as FANCD2 in open-access papers (continued):
Sharing a sentence is not in itself a finding about the gene and the disease.
endometrial cancer (9 papers, 2020 to 2024). Primary or metastatic malignant neoplasm involving the endometrium (mucous membrane that lines the endometrial cavity). "According to a tissue microarray analysis, FANCD2 overexpression was associated with lympho-vascular invasion in type I endometrial cancer and recurrence in type II endometrial cancer." (PMID 35847989, 2022). "High FANCD2 expression in endometrial cancer correlates with a poor overall survival rate." (PMID 37821996, 2023). "AEG-1 positively regulates the expression of FANCD2 and FANCI, which regulates DNA damage by platinum compounds, and knocking out AEG-1 in endometrial cancer cells significantly increased their sensitivity to cisplatin." (PMID 33918653, 2021). "Pristimerin, a traditional Chinese medicine, significantly decreased the AEG-1, FANCD2 and FANCI levels in endometrial cancer cells and restored their sensitivity to cisplatin in an in vivo xenograft model." (PMID 33918653, 2021). "A positive correlation among the levels of AEG-1, FANCD2 and FANCI were observed in breast and endometrial cancers." (PMID 33918653, 2021). "Knocking out AEG-1 increased the cisplatin sensitivity in endometrial cancer cells, but a direct role of FANCD2 and FANCI in mediating this effect was not tested by overexpression/knockdown studies." (PMID 33918653, 2021).
colon cancer (8 papers, 2018 to 2025). "Based on our findings, we propose that FANCD2 holds promise as a novel diagnostic biomarker and therapeutic target for cancers such as lung, breast, liver, and colon cancer, among others." (PMID 38443946, 2024). "Specifically, pevonedistat suppressed FANCD2 foci formation at areas of DNA ICLs and significantly reduced HCT116 colon cancer cell survival in combination with cisplatin." (PMID 37226898, 2023). "Whilst the interaction between FANCD2 and FOXO3 has not been directly linked to cancer metastasis, FANCD2 overexpression on its own has been shown to be correlated with lymph node metastasis of colon cancer." (PMID 32372224, 2020).
colorectal cancer (8 papers, 2021 to 2025). A primary or metastatic malignant neoplasm that affects the colon or rectum. "As is known, FANCD2 is the frequently mutated gene in colorectal cancer." (PMID 35154239, 2021). "HAP1 cells deficient in FANCD2, a gene essential for ICL repair, and their wild-type counterparts were infected with colibactin producing (clb+) E. coli strains isolated from a Japanese colorectal cancer (CRC) patient." (PMID 40983955, 2025). "We first confirmed that knockdown of β‐catenin in the APC‐mutant colorectal cancer cell line COLO320HSR markedly reduced the expression of BRCA1, FANCD2, and RAD51." (PMID 33660437, 2021).
non-small cell lung carcinoma (8 papers, 2014 to 2025). A group of at least three distinct histological types of lung cancer, including non-small cell squamous cell carcinoma, adenocarcinoma, and large cell carcinoma. "Our preceding research has unveiled that impeding the monoubiquitination process and the formation of nuclear foci of FANCD2 could heighten the susceptibility of non-small cell lung cancer (NSCLC) to cisplatin-induced DNA damage and apoptosis." (PMID 38443946, 2024). "We screened 139 non-small cell lung cancer (NSCLC) FFPE tumors for FANCD2 foci formation by FATSI analysis." (PMID 25566506, 2014). "Powerful metrics are available to detect FANCD2/BRCA1 foci formation, such as the FA triple-staining immunofluorescence based method (FATSI), which identified a subset of non-small-cell lung cancer (NSCLC) tumors that were deficient in FANCD2/BRCA1 foci and thus were repair deficient." (PMID 27642590, 2016). "The anticancer mechanisms of AITC in human A549 and H1299 non-small cell lung cancer (NSCLC) cells were reported to be due to S and G2/M cell cycle arrest, γH2AX, FANCD2 foci, and ATM/ATR-mediated checkpoint responses that induced replication stress in NSCLS cells." (PMID 36135016, 2022).
leukemia (7 papers, 2008 to 2025). A malignant (clonal) hematologic disorder, involving hematopoietic stem cells and characterized by the presence of primitive or atypical myeloid or lymphoid cells in the bone marrow and the blood. "This indicates the scientific and clinical benefit of studying FANCD2 and its related genes and associated mechanisms in leukemia for improving the diagnosis, prognosis, and therapeutics of leukemias." (PMID 39051418, 2024). "Similarly, in mouse models of FA, mice with only Fancd2 mutations exhibit a long latency to developing mild hematopoietic stem cell dysfunction, but adding an Adh5 or Aldh2*2 mutation results in bone marrow failure and leukemia." (PMID 40244696, 2025). "Moreover, FANCD2 overexpression has been reported in leukemia drug resistance." (PMID 39051418, 2024). "In contrast, K14E7 Fancd2+/+ adherent or IL-3 dependent nonadherent cell lines injected S.C. or I.V. produced no leukemia or solid tumors (not shown)." (PMID 27637088, 2016). "Cells from the same K14E7 Fancd2−/− clone 1 cell line injected I.V. at 1 × 106 cells in 100 μl formed multiple lung, liver, and soft tissue metastases, replaced the bone marrow with tumor cells, and produced peripheral blood leukemia with Ig kappa and lambda positive cells (not shown)." (PMID 27637088, 2016).
bone marrow failure (6 papers, 2017 to 2023). "Individuals with FANCD2 mutations typically present with a milder form of FA, characterized by a later onset of bone marrow failure and a lower risk of cancer." (PMID 37623222, 2023). "The FA-ID ubiquitination is required for prevention of bone marrow failure, and FA patients with FANCD2 mutations were reported to have an early onset of bone marrow failure." (PMID 35865631, 2022). "Mice with double knockout in ALDH2 and FANCD2 have also been found to spontaneously develop severe HSC attrition and bone marrow failure." (PMID 33573309, 2021).
breast tumors (6 papers, 2014 to 2024). "It is interesting to note that in contrast to these findings, a previous study showed that a cohort of breast tumours exhibiting reduced cytoplasmic FANCD2 expression were correlated with poor survival outcomes." (PMID 25071006, 2014). "The FA pathway has also been connected to TNBC, as comparison of mRNA expression in different breast tumor types revealed several FA pathway genes (BRCA1, FANCD2, FANCF, and PALB2) being significantly less expressed in TNBC tumors compared to luminal A (ER or PR positive) tumors." (PMID 28702895, 2017).
nasopharyngeal carcinoma (6 papers, 2014 to 2024). A carcinoma arising from the nasopharyngeal epithelium. "For example, FANCD2 silencing significantly inhibits cell proliferation, promotes apoptosis of CNE-2 cells, and the silencing of FANCD2 slows tumor growth in the xenograft tumor models of nasopharyngeal carcinoma." (PMID 36814203, 2023). "UBC13, HLTF, and SHPRH in the TS pathway, RAD51 and BRCA1 in the HR pathway, and FANCD2 in the FA pathway are highly expressed in cisplatin-resistant nasopharyngeal carcinoma (NPC) cells." (PMID 25051366, 2014).
neuroblastoma (6 papers, 2009 to 2025). Neuroblastoma (NB) is the most common solid, extracranial childhood tumor. "A marked downregulation of FANCD2 expression was also observed in shRNA-mediated ATM-knockdown neuroblastoma cells." (PMID 37020276, 2023). "Complete loss of ATM suppressed the expression of DNA repair-associated molecules FANCD2 and RAD51 and induced DNA damage in neuroblastoma cells." (PMID 37020276, 2023). "Other studies also identified a deletion/insertion in the FANCD2 gene in nephro- and neuroblastomas." (PMID 28055978, 2017). "Moreover, ATM depletion induces proteasomal degradation of FANCD2 and sensitizes neuroblastoma cells to PARPis54." (PMID 40038300, 2025). "WEE1, CHEK1, BRCA1, FANCD2, PARP1, and phosphorylation of CHEK1 and ATR were significantly reduced in TRPM2 deleted neuroblastoma and myeloid leukemia cells after doxorubicin treatment." (PMID 35428820, 2022).
head and neck cancer (5 papers, 2008 to 2025). A primary or metastatic malignant neoplasm affecting the head and neck. "To characterize the genetic dependencies of an FA-deficient versus WT genetic background, we used CRISPR-Cas9 to engineer a FA deficiency (FANCD2-null) in a well-characterized head and neck cancer cell line (FaDu)." (PMID 41188232, 2025). "We recently showed that a subset of cisplatin-sensitive head and neck cancer cell lines are defective in cisplatin-mediated induction of FANCD2 nuclear foci." (PMID 18325101, 2008). "The three head and neck cancer cell lines were treated with phenylbutyrate, cisplatin or the combination of the two and the induction of monoubiquitylation of FANCD2 was evaluated using Western blot." (PMID 18325101, 2008). "We recently showed that cisplatin sensitivity in head and neck cancer may also be linked to the FA/BRCA pathway since cisplatin-sensitive head and neck cancer cell lines were found to be defective in the formation of FANCD2 nuclear DNA repair foci." (PMID 18325101, 2008). "When cisplatin-induced monoubuitylation of FANCD2 was analyzed for the three head and neck cancer cell lines, we did not observe any inhibiting effect of phenylbutyrate." (PMID 18325101, 2008).
pancreatic cancer (5 papers, 2010 to 2025). "The heterozygous and somatic mutations of FANCD2 were reported in various malignancies, including pancreatic cancers and squamous cell carcinomas." (PMID 35236309, 2022). "Furthermore, we tested the impact of EXO1 KO in the patient-derived FANCC-deficient pancreatic cancer cell line PL1140, which has a defect in FANCD2 monoubiquitylation that can be restored by complementation with wild-type FANCC." (PMID 41006228, 2025).
prostate carcinoma (5 papers, 2014 to 2023). A carcinoma that arises from epithelial cells of the prostate gland. "We also performed the reciprocal analyses whereby we knocked down FANCD2 in the PTEN-deficient prostate carcinoma cell line PC-3 again using siRNA." (PMID 27819275, 2016). "Among the 504 non-prostate cancer cases diagnosed at our institution with the same NGS approach, three carriers of the same mutations were found, one with the FANCD2 mutation and two with the RAD51C mutation, with different cancers occurring in the families." (PMID 29659569, 2018). "Next, we confirmed the functional role of FANCD2 in resisting the toxic effects of polyamides in a model outside of prostate cancer." (PMID 25249630, 2014). "It has been revealed that DDR genes alterations including BRCA2, BRCA1, CDK12, ATM, FANCD2, or RAD51C affect almost 20% of 333 primary prostate cancer." (PMID 36739400, 2023). "In a molecular analysis of 333 primary prostate cancers, the Cancer Genome Atlas (TCGA) study showed a 19% prevalence of alterations in several DNA repair genes, including BRCA2, BRCA1, ATM, CDK12, FANCD2, and RAD51C." (PMID 37240284, 2023).
cervical carcinoma (4 papers, 2014 to 2025). A carcinoma arising from either the exocervical squamous epithelium or the endocervical glandular epithelium. "We observed that E7 induced cervical cancers and that FancD2 deficiency increased the incidence of cancer." (PMID 27190216, 2016). "The cancer incidence in Bi-L E7/K14-tTA/FancD2−/− mice was significantly higher than in the Bi-L E7/K14–tTA/FancD2+/+ mice (p = 0.009), indicating that FA deficiency facilitates development of cervical cancer." (PMID 27190216, 2016). "To examine if cervical cancers arising in Bi-L E7/K14-tTA mice on the FancD2-deficient background remain dependent upon continued expression of E7, we likewise administered doxycycline to Bi-L E7/K14-tTA/FancD2−/− mice for the last month on estrogen to repress E7 expression." (PMID 27190216, 2016). "Specifically, we put Bi-L E7/K14-tTA mice, in which we can temporally regulate expression of the dominant HPV16 oncogene, on either the FancD2-sufficient background or the FancD2-deficient background and chronically treated the mice with estrogen to induce cervical cancer." (PMID 27190216, 2016). "Notable findings include CD70, FANCD2, PFKP, MORN3, and LEF1, which exhibited strong causal associations and potential relevance in cervical cancer pathogenesis." (PMID 40817807, 2025). "Of the long genes that overlapped with FANCD2-enriched regions, 121/185 (65.4%) were expressed in C33-A and/or HeLa cells, further validating our FANCD2 peaks as sites of genetic instability in cervical carcinoma cells." (PMID 34848725, 2021). "We have previously shown that, on the FancD2-sufficient background, cervical cancers are addicted to E7; turning off expression of E7 in the context of Bi-L E7/K5-tTA mice by administering doxycycline (Dox) led to regression of cervical neoplasia." (PMID 27190216, 2016). "To assess the association of our cervical carcinoma-specific fragile-site dataset with HPV integration sites, we calculated the frequency with which an integration breakpoint occurred within 50 Kb9 of the C33-A and HeLa FANCD2-enriched regions." (PMID 34848725, 2021). "No cervical cancers were observed in FancD2+/+ and FancD2−/− mice, indicating that FancD2 deficiency alone is not sufficient to cause cervical cancer, supporting our previous observations." (PMID 27190216, 2016). "The overexpression of BRCA1, BRCA2, RAD51, BRIP1 (BACH1), FANCD2, BLM and RFC in non-responding versus responding cervical cancer samples suggests that DNA repair mechanism activation occurs through cell cycle arrest and homologous recombination." (PMID 24708616, 2014). "Immunohistological staining confirmed increased expression of BRCA1, BRIP1, FANCD2 and RAD51 in non-responsive compared with responsive advanced squamous cervical cancer, both in the initial set of 21 cervical cancer samples and the second set of 24 samples." (PMID 24708616, 2014).
lymphoma (4 papers, 2015 to 2025). A malignant (clonal) proliferation of B- lymphocytes or T- lymphocytes which involves the lymph nodes, bone marrow and/or extranodal sites.
mesothelioma (4 papers, 2012 to 2026). A usually malignant and aggressive neoplasm of the mesothelium which is often associated with exposure to asbestos. "In this study, we investigated the context-dependent interplay between BAP1 and ubiquitin-specific protease 1 (USP1) in mesothelioma cells, focusing on their roles in regulating FANCD2, cell proliferation, and DNA damage responses." (PMID 42069682, 2026). "In contrast, depletion of FANCD2 suppressed cell proliferation irrespective of BAP1 status, underscoring the essential role of FANCD2 in mesothelioma cell survival." (PMID 42069682, 2026). "Together, these findings identify USP1 as a context-dependent therapeutic vulnerability in BAP1-deficient mesothelioma and support a working model in which USP1-dependent maintenance of FANCD2 function becomes critical in the absence of functional BAP1." (PMID 42069682, 2026). "Although both BAP1 and USP1 were capable of deubiquitinating FANCD2 in vitro, USP1 suppression in mesothelioma cells did not provide clear biochemical evidence of altered FANCD2 ubiquitination." (PMID 42069682, 2026).
multiple myeloma (4 papers, 2015 to 2024). "When all 46 high-risk cases were pooled and the mean FANCD2 expression level of that pool was compared to all 305 standard-risk cases, the up-regulation of FANCD2 in high-risk myeloma was highly significant (p = 0.004)." (PMID 25838973, 2015). "The results presented here support the view that FANCD2 may be a bone fide high-risk myeloma gene that is worthy for consideration as molecular target for new, targeted therapies of patients with MM." (PMID 25838973, 2015). "Moreover, overexpression of FANCD2 appeared to be a feature of high-risk myeloma, a subset of the disease for which new therapeutic approaches are urgently needed." (PMID 25838973, 2015). "The present K14E7 Fancd2−/− malignant plasmacytomas derived from single cells expressed both kappa and lambda light chains, a phenomenon known to occur in human multiple myelomas." (PMID 27637088, 2016). "In this study, we provided clinical evidence for a role of FANCD2 in myeloma." (PMID 25838973, 2015). "Another study showed that ILF2/YB‐1/U2AF2 complex promotes DDR‐related mRNA processing that affects the expression of FANCD2 and EXO1 in multiple myeloma." (PMID 34709752, 2021).
chronic myeloid leukemia (3 papers, 2010 to 2024). "Additionally, recently, somatic FANCD2 mutation (c.2022-5C>T) emerged as a biomarker of early progression in chronic myeloid leukemia." (PMID 39768544, 2024).
esophageal cancer (3 papers, 2020 to 2023). A primary or metastatic malignant neoplasm involving the esophagus. "For example, FANCD2 mutations correlate with an increased risk of head and neck squamous cell carcinoma and esophageal cancer." (PMID 35595243, 2022). "Downregulation of FANCD2 expression significantly inhibits the proliferation of esophageal cancer cells, affecting tumor formation and metastasis, and FANCD2 is a biomarker of esophageal cancer." (PMID 37821996, 2023). "We provide evidence of a novel role of FANCD2 in esophageal cancer progression and its potential value as a biomarker for disease management." (PMID 32906798, 2020). "In order to understand FANCD2 function in esophageal cancers, we used cell line, animal model, and sequencing approaches." (PMID 32906798, 2020).
gastric cancer (3 papers, 2017 to 2023). A primary or metastatic malignant neoplasm involving the stomach. "Mutations in the FANCA and FANCD2 genes can increase the risk of gastric cancer by disrupting the DNA damage response pathway." (PMID 37623222, 2023). "The molecular mechanisms of gastric cancer development in FANCA and FANCD2 mutations are complex and require further research to fully understand." (PMID 37623222, 2023). "We detected increased expression of FANCD2, TP53BP1, and RPA2 in early gastric cancer, suggesting that DNA damage and DDR are prevalent in the course of this disease." (PMID 36061145, 2022). "The expression of TP53BP1 positively correlated with the expression of cGAS, STING, and IRF3, while the expression of FANCD2 positively correlated with the expression of IRF3 and STAT6, suggesting the major role of DDR in SASP activation in early gastric cancers." (PMID 36061145, 2022).
hypogonadism (3 papers, 2010 to 2024). A disorder characterized by decreased function of the gonads. "Likewise, the most consistent FA phenotype in murine FA gene knockout models (e.g. Fancc, Fancg, Fanca, Fancd1, Fancd2), is hypogonadism, impaired gametogenesis and infertility." (PMID 20661450, 2010).
Immune Deficiency (3 papers, 2014 to 2020). "A clinical report described a patient with a heterozygous mutation/deletion of FANCD2 who exhibited symptoms of combined immune deficiency in the absence of a HIV infection." (PMID 32165999, 2020).
liver cancer (3 papers, 2022 to 2024). An epithelial or non-epithelial malignant neoplasm that arises from the liver. "In particular, the expression of ASPM and FANCD2 were significantly upregulated in gallbladder cancer and liver cancer tissue samples versus their respective controls." (PMID 38903178, 2024). "gCn→A mutations are higher in liver cancer samples with deleterious mutations in NER, DPC repair and FANCD2 genes." (PMID 38260495, 2024). "Our results in yeast were further corroborated upon analysis of whole exome sequenced liver cancers, wherein, tumors with defects in ERCC1 and ERCC4 (NER), FANCD2 (ICL repair) or SPRTN (DPC repair) carried a higher gCn→A mutation load than tumors with no deleterious mutations in these genes." (PMID 38260495, 2024).